TNF (tumor necrosis factor)
Diseases named in the same sentence as TNF in open-access papers (continued):
Sharing a sentence is not in itself a finding about the gene and the disease.
infection (continued). "At day 4 following CB4 infection of WT NOD mice, we observed significant increases compared to uninfected controls in the levels of both TNF-α and IL-6 and to a lesser extent IFN-γ Little to no production of IL-4, IL-5, IL-10, IL-12p70 was observed following infection (data not shown)." (PMID 19122812, 2009). "In contrast, in our study pDC from blood and lymph nodes in monkeys 14 days after SIVmac251 infection were largely normal in their response to TLR7 stimulation, with lymph node pDC producing TNF-α and IFN-α together at high levels that were indistinguishable from controls." (PMID 19424421, 2009). "Thus, local and systemic levels of IL-6, IL1β, TNF-α, MIP-1α, and MIP-2 were compared between IL-4−/− and control mice at 2, 5, and 10 days after infection." (PMID 19606256, 2009). "Low levels of TNF-α gene expression were detected in response to WT and ΔPT through day 2 post-infection, but at day 4 we observed a 30-fold increase in TNF-α gene expression in response to WT infection." (PMID 19759900, 2009). "Compared to TNF and IL-1β, the secretion of IL-6 and MCP-1 by THP-1 cells infected with vMyxM013-KO virus was first detected much later, and these were only measurable after 12 hours post infection." (PMID 19851467, 2009). "In addition, in that study the intensity and level of expression of the genes analyzed (IL-8, GRO-α, GRO-β, TNF-α, IL-1β, TGF-β1 and IL-10) varied according to the step of infection (3, 10 and 24 h after the addition of bacteria to the cell culture)." (PMID 21637453, 2009). "However, in terms of polyfunctionality, i.e. the co-expression of multiple cytokines such as TNF-α, IFN-γ and IL-2, we observed a difference between the two T cell populations as the infection progressed." (PMID 19529765, 2009). "Preliminary studies revealed that plasma samples tested did not contain detectable levels of TNF-α, at either pre- or post-infection times." (PMID 19383119, 2009). "Moreover, RIGI was involved in activating both arms (NFκB/TNFα and IRF3/IFNα/β) of innate immunity following HPIV3 infection." (PMID 19922606, 2009). "Confirming the absence of MyD88, we found that TNFα was not secreted by the MyD88−/− macrophages following infection as should be expected given that TNFα induction is entirely TLR2- and MyD88-dependent." (PMID 20041145, 2009). "However, at 16 weeks post-infection (Exp-II), a significant up-regulation of both the inflammatory cytokines (IFN-γ and TNF-α) was observed in BCG immunized guinea pigs, when compared to the saline treated animals (p<0.001)." (PMID 19052643, 2008). "A similar trend was also detected with TNF-α, IL-6 and IFN-γ, 21 days after infection." (PMID 18798983, 2008). "The cytokines are divided into two important groups: theproinflammatory such as IL-1, IL-6, and TNF-α, and the anti-inflammatory such as IL-10,and have a negative impact on resistance to infection and in septic mice,reduction of IL-10 levels improves survival." (PMID 18604304, 2008). "In mice infected with the ΔsigC mutant, the levels of TNF-α, IL-1β, IL-6 and IFN-γ began to drop 14 days post infection and persisted throughout the study while a significant reduction in CCL-2 and CCL-5 levels was detected 70 days after infection." (PMID 18798983, 2008). "Since the inflammatory response might explain the rapid signs of illness in VVΔE3L infected ISG15 KO mice, we measured serum cytokine levels (IL-6, TNF-α, IL-10, MCP-1, IFN-γ, and IL-12 p 70) at early times post infection." (PMID 18604270, 2008). "PPIA, down-regulated during infection, and TNF, even if not detected as differentially expressed in our transcriptome experiment, were also chosen for validation." (PMID 18331636, 2008). "Within the testis, the levels of expression of the immunosuppressive cytokines IL-10 and TGFβ and pro-inflammatory cytokines IFNγ, IL-1β, TNFα transcripts was not significantly changed following infection." (PMID 18347738, 2008).
infection (continued). "Among them, IFN-α (1000 pg/ml at 16 h), IL1RA (750 pg/m), IL4 (13 pg/m) and the proinflammatory cytokines IL-6 (1250 pg/m) and TNF-α (1700 pg/m) were induced much more rapidly after MV-EDIII-ectoM infection and at levels 8–10 times higher than after MV-EDIII infection." (PMID 18160988, 2007). "Our sensitivity analysis indicates a critical role for TNF production by both MIs (α30) and Th1 cells (α32) throughout the infection (negative correlation values −0.6 to −0.2, p < 0.001)." (PMID 17953477, 2007). "Using the “receiving treatment” model of analysis, the crude rate of serious infection was 39.2 per 1,000 person-years in the DMARD cohort and 55.5 per 1,000 person-years in the anti-TNFα cohort, ranging from 50.4 to 63.0 events per 1,000 person-years in the 3 anti-TNFα drug cohorts." (PMID 17763441, 2007). "Immune exhaustion in P14 cells peaked at day 20 post-clone 13 infection, a time point when P14 cells in spleen and liver had almost no ability to produce IL-2 and TNF-α, and a statistically significant reduction in IFN-γ production was also observed (day 20)." (PMID 17553158, 2007). "Among the induced cytokine genes was TNF, not identified as being hypervariable but present here as a driving force for a network of genes up-regulated 1.5 hours post infection as suggested by IPA." (PMID 18047719, 2007). "Thelevels of TNFα and IL-6 as found in the presentstudy in daytime dialysate are on the whole comparable to those described in several studies in CAPD patients withstandard glucose dialysis solutions during an infection-free period." (PMID 18274646, 2007). "However, BALB/c splenocytes produced higher proinflammatory cytokines such as IL-1β, TNF-α, IL-6, IL-18 than C57BL/6 splenocytes after infection with B. pseudomallei." (PMID 16919160, 2006). "Infection with X4-Env pseudotyped HIV-1 did not lead to any detectable luciferase activity at any time point in the absence or in the presence of TNF-α." (PMID 16796744, 2006). "The effect of AddnIκB or AdLacZ infection per se on basal mRNA expression in the absence of TNF-α was within 20% for all genes investigated." (PMID 16803639, 2006). "This expression was completely inhibited in HUVECs infected with AddnIκB prior to TNF-α stimulation, while no inhibitory effect was observed after pre-infection with control virus (AdLacZ)." (PMID 16803639, 2006). "Interestingly, we observed that in vitro infection with H37Rv induced the whole blood cultures from HIV patients to synthesize increased levels of cytokines such as IL-1, TNF-α, IL-6 and IL-10." (PMID 16504020, 2006). "Thus, TNF and TNFR network provided powerful selection pressure for viruses and other pathogens to evolve strategies to combat the TNF-mediated responses to infection." (PMID 16518473, 2006). "However, we show here significant differences such as uncontrolled infection in the late phase with disseminating infection and the capacity of membrane expressing cells from the bone marrow to confer long-term -and not transient- resistance to Mtb infection in TNF deficient recipient mice." (PMID 16285886, 2005). "In line with this, mice with a targeted disruption of the TNF gene showed impaired resistance to HSV and increased viral replication within the first days of infection, and antibodies to TNF and an inhibitor of NO production impaired early control of HSV infection in peripheral nervous tissue." (PMID 16076403, 2005). "Bone marrow cells, but not lymphocytes from mem-TNF mice confer resistance to infection in TNF-KO mice." (PMID 16285886, 2005). "Notably, the mRNA expression of the pro-inflammatory factors tumor necrosis factor (TNF)-α and interferon (IFN)-α remained higher than that noted in the control group on days 3, 7, and 10 post-infection, with differences on days 7 and 10 being highly significant." (PMID 41514840, 2026).
infection (continued). "In a non-lethal infection model, azeliragon markedly reduced bacterial loads in blood and lung tissues and significantly decreased serum levels of pro-inflammatory cytokines, including TNF-α and IL-6." (PMID 42040546, 2026). "Moreover, elevated proinflammatory cytokines such as TNF-α and interferon (IFN)-γ may additionally promote CTSS processing and activation, changes that are less likely to occur during low-dose infection." (PMID 41258714, 2026). "Furthermore, an increased concentration of the pro-inflammatory cytokine TNF-α was found in the lungs of TRαKO mice at the peak of infection, whereas other cytokines, e.g. IL-1β and IL-6, were not altered." (PMID 41159501, 2025). "These emergent differences in TNFα and IFNγ parameters between LTBI and naïve simulations could be reflective of immune memory in LTBI cells, as was hypothesized for the corresponding in vitro infection." (PMID 39918314, 2025). "We found that both parent H1N1 and H1N1-E158A viruses induced cardiac IFNβ, TNF, IL-6, IL-18, and IL-1β above levels seen in mock control animals and that the H1N1-E158A virus induced higher levels of each inflammatory cytokine than the parent virus at day 5 post infection." (PMID 40909698, 2025). "Thus, while membrane TNF is sufficient for initial control of infection and granuloma organization, the absence of soluble TNF compromises long-term immunity against virulent M. tuberculosis." (PMID 40427602, 2025). "Fibroblasts synthesize pro-inflammatory cytokines such as IL-6, interferon-β (IFN-β), and tumor necrosis factor alpha (TNF-α), as well as chemokines like C-X-C motif chemokine ligand 1 (CXCL1), and secrete growth factors and metalloproteinases that support tissue repair after infection." (PMID 41305634, 2025). "Additionally, severe influenza virus infection was associated with hypercytokinemia, including increased cytokine (IFNβ, TNF, IL-10 and IL-12p70) and chemokine (MCP-1 (CCL2), KC (CXCL1), IP-10 (CXCL10) and RANTES (CCL5)) levels in the severe infection group at 7 dpi." (PMID 41285788, 2025). "Finally, the involvement of additional cytokines produced by activated CD4+ T cells, such as TNF and GM-CSF, in dictating craniotomy infection outcome remains a possibility and was not examined here." (PMID 39989461, 2025). "In the present study, Compared with Met and Mer, HC treatment can significantly improve the infection of patients with DFU, and it could significantly reduce the expression levels of inflammatory factors (TNF-α and IL-6) in the serum of patients, and reduce the inflammatory response of patients." (PMID 40745559, 2025). "pullorum infection significantly elevated (p < 0.05) the renal (CREA, UREA), hepatic (ALT, AST), immunological (IgG, IgM), and inflammatory (TNF-α, IL-6, SAA, CRP) parameters, as well as the expression of trefoil factor 3, Toll-like receptor 2, TNF-α, IL-1β, and IL-6." (PMID 41597538, 2025). "The evasion of fungal immune control mechanisms with down-regulated Th1 (IFN-γ, TNF-α, and IL-2) and Th17 T cell cytokines (IL-17A) and CXCR3+ T cell chemoattractant chemokine (CXCL10) responses, allows more vigorous replication of Cryptococcus and overwhelming infection." (PMID 39928682, 2025). "For example, compared with infection with low pathogenicity influenza virus (IAV) strains, lethal IAV strain infection preferentially upregulated TLR3 to a greater extent, which induced dysregulation of cytokines such as IL-6 and TNF-α and enhanced viral replication." (PMID 41221396, 2025). "The study concluded TNF-α lacked specificity for bacterial etiology and could not discriminate infection severity, reinforcing its limited clinical utility compared to IL-6/IL-10." (PMID 40647525, 2025).
infection (continued). "At 6 dpi, the presence of copper during the assay resulted in a significant reduction in IL-1β mRNA and proinflammatory cytokines (TNF-α and IL-12) produced in response to MtbΔctpA infection, as compared to the levels observed at the same period of infection in the absence of the metal." (PMID 40002852, 2025). "Notably, the infection-induced levels of pro-inflammatory cytokines IL-6 and TNF-α decreased time-dependently (solid lines), whereas for uninfected wounds, the levels of TNF-α significantly increased over time (dashed lines)." (PMID 40630479, 2025). "Similarly, replicating IAV induced secretion of TNFα and IL-6 from DCs but not in the presence of WT and H84T that inhibit infection." (PMID 40333697, 2025). "Thus, the reduced Th1 responses and expression of IFNG, TNF, GZMB, and PRF1 in CD4+ Trms may indicate the impaired anti-infection capacity in COPD airways." (PMID 40589761, 2025). "In addition, TNF-α inhibitors were confirmed to be connected with the increased risks of infections, including tuberculosis, varicella, non-melanoma skin cancers, and non-Hodgkin lymphoma." (PMID 40356994, 2025). "In summary, the elevated TNF-α levels in ICH patients not only indicate an immune response to UTI but also serve as a significant predictor due to its early appearance, high specificity for infection-related inflammation, and central role in the immune response." (PMID 41357523, 2025). "The role of inflammatory cytokines (such as IL-6, IL-1 β, TNF - α) in inhibiting or regulating endogenous DKK1 expression has not been evaluated, and these factors may have an impact on local inflammation progression and fibrosis after AE infection." (PMID 40496021, 2025). "Additionally, the increases of IDR responses after vaccination and the secretion of IFN-γ and TNF-α after infection were negatively correlated with the relative weights of spleens and livers." (PMID 40666521, 2025). "Additionally, infection with H9N2 AIV, whether live or inactivated, induces strong innate antiviral and inflammatory responses involving TLR3, TLR7, MDA5, TNF-α, and CCL5 stimulation." (PMID 41331407, 2025). "Interestingly, IFNγ knockout animals showed delayed bacterial clearance and survived the infection, yet mice lacking TNF succumbed to disease." (PMID 40415550, 2025). "Notably, infection-induced dysregulation of immune-related genes (e.g., TXNIP, HO-1 and Prdx5) has been reported, while deletion of the gntR10 gene elevates levels of TNF-α, IL-6 and IL-8 transcripts in infected cells." (PMID 41235247, 2025). "Thus, in the early phase of infection, the virus does not significantly disrupt the TNFα-induced activation of NF-κB." (PMID 40103806, 2025). "Finally, these types of cells are involved in the host immune response through the production of tumor necrosis factor (TNF), interleukin 6 (IL-6), and cytokines in response to any infection with enveloped RNA viruses transmitted by arthropods, as is the case with CHIKV." (PMID 41472253, 2025). "Unlike ERBs, elevated TNF, IL-6 and IL-10 cytokine responses are classical hallmarks of severe filovirus disease in both humans and NHPs following natural exposure or experimental infections." (PMID 41181097, 2025). "The BMDMs were either treated with TNF prior to infection or not." (PMID 41037321, 2025). "In addition, mangiferin was found to modulate host immune responses by simultaneously inhibiting pro-inflammatory cytokines, IL-6 and TNF-α, and upregulating the expression of anti-inflammatory IL-10 and antiviral IFN-γ, thus mitigating infection-induced inflammation." (PMID 40733492, 2025). "Another difference may be due to the timing of infection, as early stages may not yet trigger strong TNF-α responses." (PMID 40990013, 2025). "For example, enhanced TNF gene expression has been demonstrated in necrotizing tuberculomas, in the fibrotic walls of cavities characteristic of fibro-cavernous TB, and adjacent lung parenchyma not overtly affected by infection." (PMID 40427602, 2025).
infection (continued). "The mRNA abundance of TNF-α, IL-1β and IL-6 were significantly up-regulated from 6 h to 24 h post infection, while those of iNOS, Arg-1 and IL-10 did not change significantly from 18 h to 24 h post infection." (PMID 40663568, 2025). "NTM abdominal wall and hepatic abscesses have been reported among patients with HIV and patients treated with monoclonal antibodies or tumor necrosis factor inhibitors, but only as manifestations of disseminated disease rather than the initial foci of infection." (PMID 39323660, 2024). "To determine the mRNA expression levels of IFN-γ, TNF-α, IL-1β, and IL-18, as well as the abundance of cytokines IFN-γ, TNF-α, IL-6, and IL-10 in the kidneys of uninfected and PbA-infected mice at day 7 post-infection, we performed quantitative real-time PCR and CBA assays, respectively." (PMID 38787228, 2024). "Thus, we observed no significant changes in IFN-γ, TNF-α, and IL-10 expression between the two groups with double infection." (PMID 38790916, 2024). "Notably, we found that elevated TNF-α mRNA expression in the nasopharynx during the early phase of infection was a significant independent predictor of the absence of COVID-19 pneumonia." (PMID 39339947, 2024). "Transcription of genes like IRF3 and TNFα were not significantly altered upon infection." (PMID 39509467, 2024). "However, in addition to IL-12, GRA24 upregulates several other proinflammatory cytokines and chemokines, including IL-6, TNF, MCP-1, CCL5, CXCL1, and CXCL10 that could contribute to the lethal outcome of infection." (PMID 39440975, 2024). "TNF-α has been shown to act as an innate helper factor produced by Ly6C macrophages+, whose function is to favor chemokines secretion (CXC motif) ligand 2 (CXCL2), responsible for the increase in the inflammatory response and neutrophile migration to the infection site." (PMID 39337365, 2024). "TNF, together with other receptor genes such as a scavenger receptor CD163 and Fc receptors, demonstrated that a TNF-mediated inflammatory response was triggered in iMACs, and the stimulated macrophages would engulf the HCV-infected Huh7 cells to relieve the infection." (PMID 38675895, 2024). "The increase in TNF-α and IL-1β levels during PRRSV infection may contribute to the increase in macroscopic lung lesions and fever in pigs in the challenged group because of the recruitment of additional immune cells to the site of infection." (PMID 38515094, 2024). "Similarly, the expression of the tumor necrosis factor (TNF) gene and the CCL20 gene was downregulated two weeks after infection with M. gallisepticum strain Ap3AS, which may be attributed to the immunomodulatory effects of M. gallisepticum." (PMID 38474071, 2024). "Furthermore, in murine models, it has been observed that the inhibition of TNF-α leads to improved collagen deposition, concluding that in the absence of infection, high levels of TNFα hinder wound healing." (PMID 39771559, 2024). "However, surgical intensive care unit patients with the TNF2 allele did not exhibit a higher incidence of septic shock or baseline TNF-α levels after infection." (PMID 38716051, 2024). "Of the top 10 pathways enriched after infection with swH1N1 compared to control, most were related to response to RNA viruses (including SARS-CoV-2, IAV, and NOD signaling pathway) and cytokine signaling (Cytokine interactions, IL17 signaling, and TNF signaling)." (PMID 39247193, 2024). "Moreover, it is believed that the production rate of IL-10 and both IFN-γ and TNF-α by human CD4+ T cells, and the regulated shift from one to the other during the course of infection, are crucial for the development of an appropriate but self-limiting immune response." (PMID 38787228, 2024). "Furthermore, TP3 therapy reduced the activation of pro-inflammatory cytokines TNF-α, IL-6, and CXCL5 at the infection site, indicating that it may have been used in the healing of wounds." (PMID 38741875, 2024).